NR2F2 (nuclear receptor subfamily 2 group F member 2)
Diseases named in the same sentence as NR2F2 in open-access papers (continued):
Sharing a sentence is not in itself a finding about the gene and the disease.
diabetes (8 papers, 2012 to 2025). "It has been found that overexpression of Nr2f2 increases the expression of PGC-1α signals in mice with HF induced by diabetes, leading to exacerbated ferroptosis and mitochondrial dysfunction." (PMID 38659000, 2024). "Meanwhile,in vivo studies have shown that Nr2f2 promotes HF and ferroptosis in diabetes-induced HF by regulating PGC-1α signalling." (PMID 36815377, 2023). "Recently,in vitro experiments have shown that diabetes-induced HF in mice overexpressing Nr2f2 (AAV9-cTNT-Nr2f2) resulted in severe HF, ferroptosis, mitochondrial dysfunction and a strong oxidative stress response compared with control mice." (PMID 36815377, 2023). "In vivo, overexpressing Nr2f2 exhibited symptoms of severe heart failure, ferroptosis, mitochondrial dysfunction, and oxidative stress in diabetes mice." (PMID 36081650, 2022). "In the present study, we investigated the role of Nr2f2 in regulating ferroptosis in diabetes-induced heart failure mice by feeding a high-fat diet and streptozotocin intraperitoneal injection and the underlying mechanism." (PMID 36081650, 2022). "NR2F2, play significant roles in metabolic processes and cellular functions related to diabetes." (PMID 40834023, 2025). "In diabetes, Nr2f2 may be involved in the regulation of glycometabolism, oxidative stress, and inflammation in the pancreas." (PMID 36081650, 2022). "Studies have found that Nr2f2 overexpression can aggravate ferroptosis and mitochondrial dysfunction by modulating PGC-1α signaling in mice with diabetes-induced HF." (PMID 38659000, 2024).
ovarian cancer (8 papers, 2014 to 2020). A primary or metastatic malignant neoplasm involving the ovary. "Targeting NR2F2 expression in ovarian cancer cell lines enhanced apoptosis and increased proliferation." (PMID 28210221, 2017). "The pattern of NR2F2 expression was severely disrupted in ovarian cancers, in which decreased levels of stromal expression and ectopic epithelial expression were exhibited." (PMID 28210221, 2017).
congenital diaphragmatic hernia (7 papers, 2014 to 2025). A posterolateral defect of the diaphragm that allows passage of abdominal viscera into the thorax, leading to respiratory insufficiency and persistent pulmonary hypertension with high mortality. "Although pathogenic variants in NR2F2 are associated with congenital diaphragmatic hernia (CDH), multiple types of congenital heart defects, and with 46,XX sex reversal, duplication of NR2F2 is not known to be associated with a phenotype." (PMID 36910592, 2023). "As damaging variants in these genes cause congenital diaphragmatic hernia, these data imply that GATA6 haploinsufficiency causes diaphragmatic dysgenesis by disrupting NR2F2 and ZFPM2 gene programs." (PMID 33054971, 2020).
endometriosis (7 papers, 2019 to 2026). The growth of functional endometrial tissue in anatomic sites outside the uterine body. "Similarly, in JAR cells co-cultured with gestational epithelial endometriosis, NR2F2 and IGF2 were upregulated, whereas MDFI, SP3, and RDH10 were downregulated." (PMID 42282918, 2026). "Endometriosis-associated SNP-SNPinter models include 7 SNPs from 9 analyzed loci, such as rs17496332 (A > G) PRMT6, rs780093 (C > T) GCKR, rs10454142 (T > C) PPP1R21, rs3779195 (T > A) BAIAP2L1, rs440837 (A > G) ZBTB10, rs7910927 (G > T) JMJD1C, and rs8023580 (T > C) NR2F2." (PMID 41373783, 2025). "Validation in gestational epithelial endometriosis organoids showed upregulation of IGF2 and NR2F2, and downregulation of LIF." (PMID 42282918, 2026).
heart failure (7 papers, 2015 to 2024). Inability of the heart to pump blood at an adequate rate to meet tissue metabolic requirements. "ZNF416 is a zinc finger nuclease associated with fibroblast activation, and COUPTFII, encoded by the gene NR2F2, has been reported to repress glucocorticoid transcriptional activity and alter cardiac metabolism in heart failure." (PMID 38768074, 2024). "In vivo, DIHF mice overexpressing Nr2f2 (AAV9-cTNT-Nr2f2) exhibited severe heart failure and enhanced cardiac ferroptosis compared with DIHF control mice (AAV9-cTNT-ctrl), accompanied by mitochondrial dysfunction and aggravated oxidative stress reaction." (PMID 36081650, 2022). "Mice overexpressing Nr2f2 eventually develop heart failure due to impaired glycolipid metabolism and mitochondrial dysfunction." (PMID 36081650, 2022). "In this study, we revealed that Nr2f2 expression was increased in heart tissue of DIHF mice and mice overexpressing Nr2f2 exhibited symptoms of severe heart failure." (PMID 36081650, 2022). "In summary, our data indicate that expression of Nr2f2 was elevated in diabetic failing heart and Nr2f2 overexpression accentuated symptoms of heart failure and ferroptosis in diabetic mice." (PMID 36081650, 2022). "Nr2f2 is expressed at low levels in the adult heart, but expression increased under certain pathological conditions, such as heart failure." (PMID 36081650, 2022). "Findings revealed that Nr2f2 is increased in DIHF mice and Nr2f2 overexpression aggravated heart failure and promoted ferroptosis and mitochondrial dysfunction." (PMID 36081650, 2022).
hepatocellular carcinoma (6 papers, 2010 to 2024). A malignant tumor that arises from hepatocytes. "For example, NR2F2 has been shown to determine hepatoma phenotype by acting both as a transcriptional repressor of microsomal triglyceride transfer protein (MTP) and an inducer of CYP7A1." (PMID 20195529, 2010).
gastric cancer (5 papers, 2017 to 2021). A primary or metastatic malignant neoplasm involving the stomach. "Moreover, the miR-27b level was inversely associated with the expression of NR2F2 in gastric cancer tissues, indicating that miR-27b can inhibit gastric cancerous proliferation and metastasis, at least in part, by downregulating the levels of NR2F2." (PMID 27844448, 2017). "Nr2f2 has been reported to play important roles in the occurrence and development of gastric cancer, and identified as one of the potential targets of Fbxo21." (PMID 33531987, 2021). "In accordance with previous studies, the expression of Nr2f2 in 16 gastric cancer tissues was significantly higher than in the normal tissues." (PMID 33531987, 2021). "In gastric cancer, Nr2f2 was highly expressed in cancer tissues and cells, and related to poor prognosis and metastasis." (PMID 33531987, 2021). "Its expression was inversely correlated with Nr2f2 protein expression in gastric cancer, and Fbxo21 regulated Nr2f2 status by inducing Nr2f2 ubiquitination and proteasomal degradation." (PMID 33531987, 2021). "Fbxo21 expression was negatively correlated with Nr2f2 protein expression in gastric cancer tissues and cell lines." (PMID 33531987, 2021). "MiR-27b has also been shown to inhibit gastric cancer metastasis by targeting NR2F2, and suppress NSCLC invasion by targeting SP1." (PMID 31959200, 2020). "In this experiment, oncomine and Kaplan-meier database revealed that NR2F2 was up-regulated in gastric cancer and that the high NR2F2 expression contributed to poor survival." (PMID 27844448, 2017). "Then we used Kaplan-meier piotter database to determine the influence of NR2F2 on the survival of gastric cancer patients." (PMID 27844448, 2017). "Q-RT found that NR2F2 expression was significantly higher in gastric cancer tissues than in normal tissues." (PMID 27844448, 2017). "We determined the role of Nr2f2 in gastric cancer and the relation between Fbxo21 and Nr2f2." (PMID 33531987, 2021). "Considering the important role of Nr2f2 in the EMT process revealed by these studies, we supposed that the Fbxo21 may regulate gastric cancer biological process via Nr2f2." (PMID 33531987, 2021). "To determine whether Fbxo21 regulates proliferation and the EMT in gastric cancer through the Nr2f2 signaling pathway, we re-expressed or knocked down Nr2f2 in Fbxo21-overexpressing MGC-803 and Fbxo21-silenced SGC-7901 cells." (PMID 33531987, 2021). "On the other hand, miR-27b may act as suppressor gene in gastric cancer proliferation and metastasis by suppressing nuclear receptor subfamily 2 (NR2F2)." (PMID 32512882, 2020). "MicroRNA-27b was targeted and down-regulated by NR2F2 in human gastric cancer tissues and cells." (PMID 27844448, 2017). "NR2F2 was significantly up-regulated in gastric cancer tissues compared with normal tissues." (PMID 27844448, 2017). "Oncomine database and Kaplan meier-piotter defined that NR2F2 was an oncogene in gastric cancer." (PMID 27844448, 2017). "MiR-27b can inhibit the proliferation and metastasis of gastric cancer cells by suppressing NR2F2." (PMID 27844448, 2017). "The expression of NR2F2 was measured in gastric cancer patients by oncomine database." (PMID 27844448, 2017). "In addition, Fbxo21 protein expression was inversely associated with Nr2f2 protein expression in the gastric cancer tissues, but not the mRNA level." (PMID 33531987, 2021). "Thus, we confirmed that Nr2f2 was the specific ubiquitylation target of Fbxo21 in gastric cancer." (PMID 33531987, 2021). "Nuclear receptor subfamily 2 (NR2F2, also known as COUP-TFII) is involved in the development of many types of cancers, but its role in gastric cancer remains elusive." (PMID 27844448, 2017). "According to Spearman's rank correlation analysis, there was a strong negative correlation between Fbxo21 and Nr2f2 protein levels in gastric cancer tissues." (PMID 33531987, 2021).
gastric cancer (continued). "We examined the Nr2f2 protein levels in 16 gastric cancer tissues and matched normal tissues via immunohistochemistry." (PMID 33531987, 2021).
Obesity (5 papers, 2015 to 2022). Accumulation of substantial excess body fat. "Chicken ovalbumin upstream promoter-transcription factor II (COUP-TFII, also known as NR2F2, nuclear receptor subfamily 2 group F, member 2) is a nuclear orphan receptor that belongs to the steroid/thyroid hormone superfamily and may contribute to the pathogenesis of obesity." (PMID 26719988, 2015).
atherosclerosis (4 papers, 2015 to 2025). A disease characterized by the build-up of fatty material and calcium deposition in the arterial wall resulting in partial or complete occlusion of the arterial lumen. "Altered Nr2f2 expression may lead to congenital heart defects (CHD) and susceptibility to atherosclerosis due to the impact of Nr2f2 on lipid metabolism and inflammation." (PMID 36081650, 2022).
colorectal cancer (4 papers, 2011 to 2025). A primary or metastatic malignant neoplasm that affects the colon or rectum. "NR2F2, a ligand-inducible nuclear receptor of the steroid/thyroid hormone receptor superfamily, is mechanistically linked to colorectal cancer progression through its role in TGF-β-dependent EMT, a process critical for tumor cell invasion, metastasis, and poor clinical outcomes." (PMID 41031085, 2025).
Infertility (4 papers, 2008 to 2023). "NR2F2, Nuclear Receptor Subfamily two Group F Member 2, is an important regulator of differentiation, which has been linked to tissue homeostasis and its abnormal expression may lead to infertility, aberrant development of the vascular system, and metabolic diseases." (PMID 36923793, 2023). "Inactivation of Nr2f2 during prepubertal stages of male sexual development results in infertility, hypogonadism, and a block in spermatogenesis due to a failure of progenitor Leydig cells to mature." (PMID 36110220, 2022).
influenza (4 papers, 2020 to 2025). An acute viral infection of the respiratory tract, occurring in isolated cases, in epidemics, or in pandemics; it is caused by serologically different strains of viruses (influenzaviruses) designated A, B, and C, has a 3-day incubation period, and usually lasts for 3 to 10 days. "The activation of COUP-TF2 may have other beneficial effects in the context of the infected lungs as a loss of COUP-TF2 (also known as Nr2f2) during influenza infection contributes to endothelial dysfunction." (PMID 37515150, 2023). "Our data show that COUP-TF2 (Nr2f2) is down-regulated in lung ECs after influenza injury and slowly recovers concurrent with endothelial proliferation." (PMID 33239293, 2020).
melanoma (4 papers, 2023 to 2025). A malignant, usually aggressive tumor composed of atypical, neoplastic melanocytes. "Our functional and molecular studies suggest that NR2F2-Iso2 drives metastatic melanoma progression by modulating the activity of full-length NR2F2 (Isoform 1) over EMT- and NCC-associated target genes." (PMID 37015919, 2023). "Our data suggest NR2F2-Iso2 enhances melanoma metastasis by regulating the DNA-binding ability of the full-length NR2F2-Iso1, promoting the expression of EMT and NCC gene sets." (PMID 37015919, 2023). "Our findings indicate that DNA methylation changes play a crucial role during metastatic melanoma progression, and their control of NR2F2 activity allows transformed melanocytes to acquire NCC-like and EMT-like features." (PMID 37015919, 2023). "To probe deeper into NR2F2-Iso2 regulated genes in melanoma, we identified NR2F2-Iso2 signature genes that were consistently down-regulated in shNR2F2-Iso2 compared to shSCR in 4L and 12-273BM cells." (PMID 37015919, 2023). "Collectively, these data suggest that epigenetic NR2F2-Iso2 re-activation supports the expression of EMT genes in human melanoma." (PMID 37015919, 2023). "Here the authors compare DNA methylation profiles of NCCs and melanocytes, as well as primary and metastatic patient tissues and identify that DNA methylation changes of NR2F2 isoform 2 influence cell state transitions and melanoma metastatic spread." (PMID 37015919, 2023). "To unbiasedly address this notion in melanoma, we began to identify gene sets that were directly regulated by NR2F2-Iso1 in an NR2F2-Iso2-dependent manner." (PMID 37015919, 2023). "qRT-PCR and western blotting showed that 5-aza treatment increased NR2F2-Iso2 expression, supporting the idea that CpG demethylation is required for the re-expression of NR2F2-Iso2 in melanoma cells." (PMID 37015919, 2023). "Here, we define DNA methylation changes that accompany metastatic progression in melanoma patients and discover Nuclear Receptor Subfamily 2 Group F, Member 2 – isoform 2 (NR2F2-Iso2) as an epigenetically regulated metastasis driver." (PMID 37015919, 2023). "The scaled average expression of these NR2F2-Iso2 signature genes correlated directly (r = 0.55, p < 0.001) with the scaled NR2F2-Iso2 expression and inversely (r = −0.38, p < 0.001) with NR2F2-Iso2 methylation status across melanoma patient samples from TCGA." (PMID 37015919, 2023). "Taking a global, unbiased approach, our NR2F2-Iso1 ChIP-seq and RNA-seq studies in control and shNR2F2-Iso2 expressing melanoma cells suggest NR2F2-Iso2 affects NR2F2-Iso1 target gene expression in a context-dependent manner." (PMID 37015919, 2023). "The five NR2F2 CpGs that we found to be hypomethylated in metastatic compared to primary melanomas are located right at the NR2F2-Iso2 TSS." (PMID 37015919, 2023). "Our analyses exposed a pro-metastatic program in melanoma where aberrantly expressed NR2F2-Iso2 regulates the transactivating capacity of NR2F2-Iso1 over differentiation (e.g., PMEL) and metastasis (e.g., SNAI1) - regulating gene sets." (PMID 37015919, 2023). "Collectively, our correlative studies with clinical specimens and functional studies in xenograft models identified NR2F2-Iso2 as a metastasis driver in melanoma." (PMID 37015919, 2023). "Epigenetic reactivation of NR2F2-Iso2 unleashes a metastatic program in melanoma that restores the phenotypic plasticity and enables the acquisition of NCC-like features." (PMID 37369946, 2023). "This elegant mechanism appears to auto-regulate NR2F2 activity and may support reversible phenotypic changes and plasticity in melanoma, in addition to irreversible genetic alterations that drive tumor initiation and progression." (PMID 37015919, 2023). "To determine whether CpG methylation prevents NR2F2-Iso2 expression, we treated two melanoma cell lines and two STCs with the DNA demethylating agent 5-aza-2′-deoxycytidine for 72 h." (PMID 37015919, 2023).
melanoma (continued). "Furthermore, integration of global CpG methylation with mRNA expression data generated by TCGA16 showed that NR2F2-Iso2 hypomethylation correlates with the transcriptional upregulation of NR2F2-Iso2 in melanoma (p < 0.001)." (PMID 37015919, 2023). "Collectively, our studies suggest that an increasing ratio of NR2F2-Iso2 over NR2F2-Iso1 increases the colony forming and metastatic potential of melanoma cells, and that these features are dynamically regulated dependent on the methylation of CpGs at the NR2F2-Iso2 TSS." (PMID 37015919, 2023). "To functionally test whether NR2F2-Iso2 expression affects melanoma growth in xenograft models, we transplanted shSCR or shNR2F2-Iso2 expressing 4L cells subcutaneously into NSG mice to measure differences in tumor growth over time." (PMID 37015919, 2023). "Furthermore, NR2F2-Iso2 CpGs were more frequently hypomethylated (i.e., mean β value < 0.33) in metastatic (191 of 364; 52.5%) compared to primary (32 of 109; 29.4%) melanoma samples (p < 0.0001), while NR2F2-Iso1 CpGs were consistently hypomethylated in both, primary and metastatic samples." (PMID 37015919, 2023). "We found that Nr2f2 and NR2F2-Iso2 signature genes are significantly enriched in NC- and EMT-like melanoma cell states." (PMID 37015919, 2023). "We found that the NR2F2-Isoform2 (NR2F2-Iso2) becomes hypermethylated and silenced during NCC-to-melanocyte differentiation, but demethylation occurs in the transition from primary to metastasis in melanoma." (PMID 37369946, 2023). "LASSO regression analysis was used to filter TFs further in order to identify a biomarker that could predict the prognosis of patients with melanoma, based on which seven TFs (TBX21, MYB, GFI1, NFE2L3, TFAP2C, HEY2, NR2F2) were selected." (PMID 37435067, 2023).
squamous cell carcinoma (4 papers, 2022 to 2026). A carcinoma arising from squamous epithelial cells. "A similar role for Nr2f2 has been observed in malignant squamous carcinoma, where NR2F2 enhanced tumor cell proliferation and stemness, while suppressing differentiation." (PMID 40295478, 2025). "NR2F2 can also promote tumor cell proliferation, epithelial-mesenchymal transition, and invasive characteristics and inhibit tumor differentiation and immune cell infiltration by regulating transcriptional programs commonly found in mouse and human squamous cell carcinomas." (PMID 36011369, 2022).
ventricular septal defect (4 papers, 2014 to 2021). The presence of a defect (opening) in the septum that separates the two ventricles of the heart. "In the same patient, ventricular septal defects may be due to the NR2F2 deletion, a gene recently associated with non-syndromic atrioventricular septal defects (AVSDs)." (PMID 25435912, 2014). "In human cases and mouse models, NR2F2 has been crucially implicated in angiogenesis and heart development, and abnormal expression or depletion of NR2F2 leads to AVSD (atrioventricular septal defect) and VSD (ventricular septal defects)." (PMID 29866040, 2018). "NR2F2 has been crucially implicated in angiogenesis and heart development in humans and mouse models, and abnormal expression or depletion of NR2F2 has been reported to lead to AVSD (atrioventricular septal defect) and VSD." (PMID 33902696, 2021). "In a patient with ventricular septal defect (VSD), aortic coarctation, and neurological symptoms, we identified a de novo missense substitution p.(Val224Asp) in the ligand binding domain of NR2F2." (PMID 32037394, 2020).